CORT (cortistatin)
Diseases named in the same sentence as CORT in open-access papers (continued):
Sharing a sentence is not in itself a finding about the gene and the disease.
infection (4 papers, 2013 to 2022). The state of being infected such as from the introduction of a foreign agent such as serum, vaccine, antigenic substance or organism. "The levels of CORT in plasma were determined after development of several effects, so although infection was associated with decreased food intake, increased presence of shed skin, and weight loss, it is unclear whether increased CORT secretion was a cause or consequence of these parameters." (PMID 23630628, 2013). "Thus, CORT, in its regulatory role of maintaining ion homeostasis, may be elevated in response to disease caused by infection, and could contribute to Bd-induced mortality." (PMID 23630628, 2013). "In line with this, CORT secretion following adult LPS exposure seems independent of the early-life history of exposure to stress or infection." (PMID 25620909, 2014). "Early-life infection generally leads to a direct elevation of circulating glucocorticoids in early-life and while basal CORT was not affect by early-life infection at P14, the level of phosphorylated GR is significantly higher in the prefrontal cortex, but not the hippocampus." (PMID 25620909, 2014). "In contrast, early infection does not affect basal and/or stress-induced CORT in a lasting manner." (PMID 25620909, 2014).
cancer (3 papers, 2016 to 2022). A tumor composed of atypical neoplastic, often pleomorphic cells that invade other tissues. "CORT up-regulation is a useful biomarker for cancer cells sensitive to ifosfamide." (PMID 36686667, 2022).
metabolic disorders (2 papers, 2012 to 2021). "Furthermore, PRL, CORT, and metabolite parameter levels can also serve for early diagnosis and prognosis of blood changes due to metabolic disorders during these physiological stages." (PMID 34840462, 2021).
neurodegenerative disease (1 paper, 2015). A disorder of the central nervous system characterized by gradual and progressive loss of neural tissue and neurologic function. "Notably, the ‘neuroactive ligand-receptor interaction’ term contained genes, including cortistatin, which is associated with neuronal apoptosis and neurodegenerative disease." (PMID 25777551, 2015).
peripheral neuropathies (1 paper, 2021). "On the other hand, endogenous production of cortistatin is critical in defining nociceptive and neuroregenerative responses and to understanding processes that occur during nerve repair in peripheral neuropathies." (PMID 34202793, 2021).
CORT also shares sentences with these, for which no sentence is quoted: immune disorders (2 papers); Alzheimer disease (1); brain ischemia (1); hypercortisolemia (1); Hyperglycemia (1); Hypertension (1); Insulin resistance (1); mood disorder (1); pneumonia (1); post-traumatic stress disorder (1); prostate tumor (1); telomere syndrome (1).